SMO (smoothened, frizzled class receptor)
Diseases named in the same sentence as SMO in open-access papers (continued):
Sharing a sentence is not in itself a finding about the gene and the disease.
tumor (331 papers, 2010 to 2026). "While most studies on HHI resistance have focused on tumor‐intrinsic mechanisms, including canonical mutations in SMO, SUFU, or GLI2 that reactivate HH signaling, these alterations alone do not fully explain clinical variability in treatment response." (PMID 41543881, 2026). "These inhibitors target SMO, thereby reducing tumor size by disrupting the release of glioma-associated oncogene homolog 1 (Gli1)." (PMID 40522768, 2025). "This is supported by two key studies from the Reiter and Alvarez-Buylla labs, showing that subtypes of medulloblastoma and basal cell carcinoma (BCC) with activating SMO mutations are dependent on cilia for tumor formation." (PMID 40301543, 2025). "In human tumours, the Hh pathway is disrupted either through mutations of signalling proteins such as SMO, PTCH1 and SUFU or through overexpression of HH." (PMID 39234399, 2024). "PDT-mediated cytotoxicity reduces the population of cells driven by PTCH1 and SMO mutations, leading to tumor shrinkage and resolution in many cases." (PMID 39682631, 2024). "BCC, the most common skin cancer, is primarily driven by mutations in the PTCH1 or SMO genes, resulting in uncontrolled activation of the Hedgehog pathway and thus promoting tumor formation." (PMID 37568743, 2023). "It is worth noting that both Vismodegib and Sonidegib inhibit tumor growth by binding to the SMO receptor; thus, cancer cells with mutations downstream of SMO are resistant to these antagonists." (PMID 36635683, 2023). "The administration of the SMO inhibitor vismodegib was associated with a decrease in tumor growth and a reduction in tumor progression in a rat model of mesothelioma." (PMID 38136262, 2023). "BCC is characterized by dysregulated activation of the Hedgehog signaling pathway due to mutations in PTCH1 or SMO genes, leading to uncontrolled cell proliferation and tumor formation, making the pathway a target for BCC treatments." (PMID 37568743, 2023). "Sequencing of this recurrent tumor revealed an enrichment for the SMO W535L mutation, revealing that vismodegib treatment enriched for resistant cells undetectable by traditional histology." (PMID 36455049, 2022). "Although the loss of cilia during tumor formation is not completely unexpected, the mechanistic insights of resistance demonstrate an interesting finding that cilia loss protects tumor cells from SMO inhibitors." (PMID 35163655, 2022). "According to the literature, a significant proportion (10%) of BCC tumours occur due to gain-of-function mutations in SMO, causing uncontrolled proliferation of skin cells." (PMID 36294790, 2022). "We further uncovered that tumors with SMO mutations were more likely to be associated with increased tumor immunogenicity, enhanced antitumor immune microenvironment, and activated antitumor immune signaling pathways." (PMID 36405701, 2022). "Targeted sequencing revealed six PTCH1 variants of interest, and two SMO variants of interest in the pre-treatment tumor." (PMID 36455049, 2022). "The overexpression of Smo has been linked to the tumor size, metastasis, invasiveness, and recurrence of disease, and SMO inhibitors have been used to suppress cancer formation, trigger apoptosis, and suppress cancer stem cell activity." (PMID 36325671, 2022). "The restoration of SMO expression in SMO‐deficient CML animal models promoted tumor growth and led to a four‐fold increase in CSC proportions." (PMID 36226253, 2022). "In fact, infant (35%) and children (45%) have mutations in the downstream SMO pathway, which makes tumours intrinsically resistant to SMO inhibitors." (PMID 34944941, 2021). "Of these, SMO mutations are associated with the anterior skull base, have been shown to have an impact on the onset of tumor recurrence and both AKT1E17K and SMO are currently investigated as candidates for targeted therapy (ClinicalTrials.gov: NCT02523014)." (PMID 32245394, 2020).
tumor (continued). "Overexpression of SMO is associated with tumor size, lymph node metastasis and postoperative recurrence." (PMID 32962123, 2020). "Cilia is the primary site where activated SMO is trafficked to initiate downstream signalling, cilia loss enables low but constitutive Hh signalling protecting tumour cells from the action of vismodegib or sonidegib." (PMID 31362788, 2019). "Sequencing of the tumor DNA revealed a novel nonsynonymous SMO mutation replacing aspartic acid with histidine at amino acid position 473 (SMOD473H)." (PMID 30991683, 2019). "Molecular analysis of a recurrent tumour biopsy revealed the presence of a point mutation in SMO (D473H) that reduced the affinity for vismodegib." (PMID 30068568, 2018). "We compared our results with Vogelstein's results; all the genes had consistent classification except gene SMO, which was classified as an oncogene in Vogelstein's paper but a tumor suppressor gene in the tumor-associated gene database we used." (PMID 28978153, 2017). "The Asp477Gly mutation in the 7TM binding-site of SMO, initially isolated from a patient whose tumor had become resistant to vismodegib, reduces binding and responsiveness to a subset of 7TM ligands, including SAG and vismodegib." (PMID 27705744, 2016). "In a subsequent clinical trial for metastatic BCC, vismodegib treatment resulted in tumor regression; however, after three months, a novel SMO mutation was discovered in the tumor tissue and the treatment progress ceased." (PMID 26891329, 2016). "In particular, one of the first reports that studied the function of Kif3a in mouse medulloblastoma showed that constitutively active SMO-driven tumor formation is inhibited by loss of KIF3a." (PMID 26760767, 2016). "Several of these agents have induced tumour response in patients with tumours that harbour mutations in SMO and PTCH1, such as BCC and MB." (PMID 25660620, 2015). "There were also two processes associated to bone “myelopoiesis of bone marrow” (associated genes NPM1, RARA) and “quantity of trabecular bone” (associated genes CREBBP, SMO)—these findings were present only in the tumour tissue." (PMID 25496518, 2014). "A clinical trial with vismodegib (GDC-0449) in a medulloblastoma patient resulted in a rapid reduction of tumor mass, but led to drug resistance due to SMO mutation." (PMID 23303278, 2013). "We also genotyped a collection of primary tumors for the presence of these mutations and found one tumor sample that carried the SMO insertion mutation." (PMID 23826113, 2013). "As inhibition of SMO has been linked to an increase in vascularization in poorly vascularized tumors, we investigated the vascularization of the tumor tissue upon MS-0022 treatment." (PMID 21698280, 2011). "However, one of the challenges in the long-term use of vismodegib is the development of resistance, either through acquired mutations in the Smoothened (SMO) gene or the selection of pre-existing SMO mutations within the tumor." (PMID 39091908, 2024). "By potentially increasing the tumor’s susceptibility to SMO inhibitors, this combinatorial treatment strategy could reduce drug duration, minimize side effects, and decrease tumor recurrence." (PMID 39086988, 2024). "Conversely, loss of SMO in the tumor cells led to significant decreases in tumor number and size." (PMID 36010600, 2022). "The analysis of primary tumor and pre-treated liver metastasis revealed the SMO mutation." (PMID 35163655, 2022). "Yet, according to the COSMIC database, mutations in the SMO gene have been identified in 35 out of 45 (78%) primary cancer tissue types, which highlights the importance of further investigation into the functional role of Smo mutants in various tumours." (PMID 36294790, 2022). "However, SMO mutations driving drug resistance are common, and up to 21% of patients treated with vismodegib were found to undergo tumor regrowth during treatment." (PMID 35687691, 2022).
tumor (continued). "Interestingly, a genomic analysis proved that most cases of recurrent BCC harbored mutations in SMO, when only 15% of previously untreated neoplasms showed these alterations." (PMID 36291078, 2022). "Mutations affecting proteins involved in HH signaling, including loss of the negative regulator PTCH1 and the activating point mutation in SMO (W535L for human SMO and W539L for mouse Smo), result in hyperactivation of the HH pathway and can lead to cilia-dependent tumor formation in MB." (PMID 34638386, 2021). "The precise mechanism by which PIK3CA and SMO mutations interplayed to promote tumor progression in our patient is unknown." (PMID 29515801, 2018). "However, despite an initial clinical response, the use of SMO inhibitors has been associated with the acquisition of tumor drug resistance as a result of structural mutations in SMO10–12." (PMID 29396391, 2018). "The analysis of these resistant tumor lines led to the identification of five missense mutations of mouse SMO different from the vismodegib-induced SMO mD477G mutation, underlining the distinct modes of action of the two SMO inhibitors." (PMID 30558232, 2018). "Factors that regulate SMO levels, like Arl13b, may be important in tumor progression, as upregulated SMO expression is associated with decreased overall survival of GBM patients." (PMID 30410731, 2018). "In addition, while loss of PTEN in Ptch1+/− mice results in MB that respond to SMO inhibitors by stopping growth, the treated tumours fail to regress." (PMID 30068568, 2018). "In accordance to earlier studies the BRAF-V600E mutation was frequent (20 out of 41 samples; 49%) in the tumour samples predominantly in the mandible region, whilst the SMO-L412F mutation was detected in two (5%) of the tumour samples only, exclusively in the maxilla region." (PMID 27965463, 2017). "We also detected a SMO mutation in one MMe cell line which was also present in a tumor sample." (PMID 23826113, 2013). "However, tumor cells frequently acquire resistance to SMO inhibitors through SMO mutation." (PMID 37853413, 2023). "Because wild‐type SMO (SMOWT) and SMO with oncogenic mutation (SMOW535L) show distinct functions during tumor development and drug response, we hypothesized that both mutants should produce different downstream transcriptomes, which might provide new insight on SMO function and regulation." (PMID 35419951, 2022). "However, loss or inactivation of Fbxw7 could have an antitumor or protective effect in Hedgehog-dependent tumors including tumors dependent on inactivating mutations in PTCH1 or activating mutations in SMO, which both require an intact cilium for tumor growth." (PMID 34518642, 2021). "Similarly, tumours with an activating mutation in the HH pathway downstream of SMO, such as SUFU loss, or tumours that develop resistance to SMO inhibitors, may be responsive to GANT61 or similar inhibitors that target GLI1." (PMID 30068568, 2018). "In addition, GLI1/2 inhibitors may also be effective in tumours harbouring activating mutations in SMO, or downstream mutations in the HH pathway, as well as in tumours that have acquired resistance to SMO inhibitors." (PMID 30068568, 2018). "Inhibitors of Gli transcription factors, such as the Gli DNA binding inhibitor GANT-61 and arsenic trioxide, may significantly reduce self-renewal in tumours with mutations that are located downstream of SMO, or which simply acquire resistance to SMO-targeted molecules." (PMID 27766946, 2016). "In addition, we investigate whether the diet can work in synergy with a SMO inhibitor to cause tumor regression." (PMID 26192445, 2015). "The non-canonical Hedgehog pathway (nCHHP) can be SMO-independent, in which case both PTCH1-PHH-mediated and SMO-dependent cell proliferation affect calcium channels, chemotacticity, and cell migration, thus leading to tumoural survival and proliferation." (PMID 41008748, 2025).
tumor (continued). "For instance, in HER2-positive GC, SMO inhibition reduced tumour growth and restored trastuzumab sensitivity by inactivating the AKT/mTOR pathway." (PMID 40426308, 2025). "SMO inhibitors function by inhibiting the activation of this pathway, resulting in the suppression of tumor growth." (PMID 41383502, 2025). "IHC analysis of ES patient tumor samples confirmed high levels of SMO and GLI1, which correlated with high C1GALT1 expression." (PMID 39894896, 2025). "They demonstrated that the oncogenic activation of SMO via a constitutively active mutant (SmoM2) leads to different tumour behaviour depending on the anatomical site." (PMID 40649051, 2025). "To conclude, this study underscores the potential of Hh inhibitors, Vis and Cyc, to enhance trastuzumab’s anti-tumour activity via SMO-regression and AKT/mTOR pathway inactivation." (PMID 40426308, 2025). "There has been a growing interest in inhibiting the SHh pathway downstream of SMO, largely because some tumours, including PDAC, have shown activation of the Gli transcription factor independent of SMO." (PMID 41561521, 2025). "Emerging research depicts that the PI3K-AKT-mTOR signaling pathway regulates GLI1 expression independently of SMO in numerous cancers, promoting tumor development and progression 42-44." (PMID 39744485, 2025). "Hh pathway components Gli1 and SMO were increasingly present in both tumor types, but more prominently in MIBC, suggesting a correlation between cilia-dependent Hh signaling and tumor progression." (PMID 40301543, 2025). "As predicted by the in vitro studies, we found that SMO overexpression led to a significantly greater tumour weight and volume than trastuzumab+Vis and trastuzumab+Cyc groups." (PMID 40426308, 2025). "Itraconazole inhibited the activity of all known SMO resistance mutants at levels similar to SMO-D477G, resulting in inhibited tumour growth and reduced tumour volumes in SMO-resistant tumours." (PMID 39568072, 2024). "Cyclopamine was among the first compounds that disrupted SMO, resulting in decreased tumor proliferation and progression." (PMID 39677192, 2024). "Sox2 expression defines both tumor-initiating and tumor-propagating MB cells capable of self-renewal and resistance to SMO inhibitors." (PMID 38689348, 2024). "Primary cilia, crucial for HH pathway signal transmission, are lost during tumour development, unexpectedly shielding tumour cells from SMO inhibitors." (PMID 39568072, 2024). "Genetic analysis of resistant tumours has revealed several mechanisms that confer resistance to SMO inhibitors like GDC-0449." (PMID 39568072, 2024). "Mutations in components of this pathway, particularly Patched1 (PTCH1) and Smoothened (SMO), lead to uncontrolled cell proliferation and tumor formation." (PMID 39682631, 2024). "Although small-molecule SMO inhibitors have exhibited promising anti-tumor activity in SHH-MB, certain mutations within the SHH pathway can limit the efficacy of SMO inhibition, resulting in therapy resistance." (PMID 39107797, 2024). "Taken together, these data provide evidence that simultaneous inhibition of DNMT1 and SMO synergistically inhibits SHH-MB tumor growth specifically by blocking SHH pathway output." (PMID 39107797, 2024). "Nevertheless, cilia demonstrated tumour-suppressive activity when the Hh pathway was dysregulated downstream of SMO/PTCH1." (PMID 39234399, 2024). "Combining GDC-0449 with HhAntag, which targets SMO via multiple binding sites, shows promise in overcoming drug resistance, with high-dose HhAntag demonstrating complete tumour eradication and prolonged MB-free survival." (PMID 39568072, 2024).
tumor (continued). "For example, GDC-0449 (Vismodegib), a SMO antagonist that suppresses the activation of downstream Hh target genes, displays anti-tumor activity in locally advanced and metastatic BCC [NCT00607724]." (PMID 37305676, 2023). "SMO inhibitors have shown encouraging results in the treatment of BCC and MB, both tumours associated with type I Hh activation (mutation-driven)." (PMID 36765685, 2023). "Secreted HH mediates G‐coupled receptor‐like signal transducer Smoothened (SMO) to activate Gli, followed by nuclear translocation and stimulation of tumor‐promoting gene transcription." (PMID 37846367, 2023). "SMO inhibition causes the transcription factors GLI1 and GLI2 to remain inactive, preventing tumour-mediating genes’ expression within the Hedgehog pathway." (PMID 37240278, 2023). "Targeting the Sonic hedgehog (SHH)-Smoothened (SMO) signaling axis has also been shown to increase cancer cell proliferation and tumor formation by inhibiting SHH-SMO-mediated activation of the tumor-suppressive phenotype in myofibroblasts." (PMID 37723510, 2023). "Tumor volume and tumor weight were both reduced compared to the control group in conjunction with reduced cell proliferation and IHC signal expression of SMO, PTCH1, and GLI1." (PMID 36986819, 2023). "In fact, much controversy exists about the results observed with SMO inhibitors in tumours other than BCC and MB." (PMID 36765685, 2023). "In this particular cancer types, SMO inhibition has demonstrated strong clinical potential and, specifically for these tumours, three SMO inhibitors have already reached the clinical setting, rendering encouraging results." (PMID 36765685, 2023). "Treatment of tumor-bearing mice with the SMO inhibitor sonidgeib resulted in reduced tumor growth and significantly improved survival in both the D12M allograft and MG63 and B143 xenograft models, but not in mice with CaOS18, U2OS or SJSA tumors." (PMID 37845394, 2023). "The mutation incidence in tumor samples was as follows: NF2 R57* (15/27), PIK3CA E545K (13/27), BRAF Hotspot mutations (10/27), SMO L412F (9/27), SMO W535L (7/27), with varying mutant allele frequencies represented by the dot sizes." (PMID 38259646, 2023). "SMO gene is one of the genes in Hedgehog (HH) signaling pathway whose expression correlates with tumor size, metastasis, and recurrence." (PMID 37202799, 2023). "SMO then activates the GLI (glioma-associated oncogene homolog) family of transcription factors (TFs) to promote proliferation and tumor growth." (PMID 35687691, 2022). "When tumor cells lose their primary cilia, a ”persister” state with low output of the Hh signaling is maintained, allowing the tumor cells to evade inhibition by SMO antagonists." (PMID 35163655, 2022). "SMO mutations and a binding site for HHI are the most common causes of resistance both in BCC and other Hh-dependent neoplasms, mainly medulloblastoma." (PMID 36291078, 2022). "Except for those cancers without normal tissue data available, significant differences in the expression of SMO were detected between tumor and normal tissue in 11 types of cancer." (PMID 36405701, 2022). "In a phase 2 clinical trial with vismodegib in BCNS, histological analysis of one resistant tumor showed persistent BCC after an initial response, and an SMO mutation was identified." (PMID 35163655, 2022). "The approved SMO inhibitors are being tested in other tumor types, and novel SMO inhibitors are developing." (PMID 36254250, 2022). "Statin treatment by simvastatin reduces SHH MB cells proliferation and SHH-derived MB young mice tumor growth, as single agents or combined with SMO antagonists." (PMID 36340043, 2022). "In HCC, the high expression of SMO and GLI1, members of the Hedgehog signalling pathway, directly triggers the formation of larger tumours and is significantly associated with recurrence." (PMID 35459884, 2022).